LBH (LBH regulator of Wnt signaling pathway)
Diseases named in the same sentence as LBH in open-access papers (continued):
Sharing a sentence is not in itself a finding about the gene and the disease.
tumor (continued). "Importantly, as observed in primary tumors, tumor lines with LBH DNA hypomethylation showed a drastic increase in LBH mRNA, as determined by qPCR." (PMID 37268816, 2023). "Similarly, hypoxia-induced LBH, a highly conserved transcription cofactor, participates in embryonic development and promotes tumor progression of GBM, and hypoxia upregulates the expression of PLAT in GBM cells." (PMID 35874629, 2022). "Thus, we reached the conclusion that the overexpression of the LBH gene is associated with attenuated angiogenesis, EMT progression and VEGFA expression in NPC tumor xenografts." (PMID 34975330, 2022). "Immunostaining with anti-CD34 showed that in both CNE2 and SUNE1 tumor xenografts, tumors constructed with LBH-overexpressing cell lines presented markedly decreased MVDs in vascular hot spots compared to the negative controls, indicating attenuated angiogenesis in LBH-overexpressing tumors." (PMID 34975330, 2022). "Since LBH functions as a tumor suppressor for NPC 21, LBH downregulation in NPC cells might decrease the LBH levels in normal nasopharyngeal epithelial cells via exosome secretion in the tumor microenvironment, thereby advancing NPC progression." (PMID 34975330, 2022). "LBH has been shown to regulate FLS growth by acting as a tumor suppressor." (PMID 29554943, 2018). "Based on our research, we postulate that specifically upregulating LBH during NPC therapy might ameliorate tumor metastasis and angiogenesis, achieving better therapeutic efficacy for NPC patients via exosome-mediated VEGFA inhibition, and this is likely our next research topic." (PMID 34975330, 2022). "Furthermore, the expression of LBH was reduced by LBH knockdown in the tumor tissues of mice." (PMID 34739189, 2022). "This is in discrepancy with a published study, reporting LBH is downregulated in PRAD (based on a limited number of clinical samples), and to have tumor suppressive effects when overexpressed as LBH-GFP fusion protein in PC3M cells." (PMID 37268816, 2023). "Compared with normal tissues, IGFBP7, LBH and TFPI are low expressed in tumor tissues (P < 0.05), while KRT18, UBE2C and UBE2S were highly expressed in tumor tissues (P < 0.05)." (PMID 38077434, 2023). "In contrast, LBH was not expressed in normal colon mucosa of adjacent tissue, indicating it is a tumor-specific marker." (PMID 37268816, 2023). "In a previous study, we demonstrated that LBH participates in regulating tumorigenesis, epithelial-mesenchymal transition (EMT) and metastasis of NPC as a tumor suppressor 10, which encouraged us to further investigate its role during tumor angiogenesis in NPC." (PMID 34975330, 2022). "Hence, we concluded that in NPC tumors, LBH-mediated inactivation of CRYAB and VEGFA in HUVECs can be induced by LBH+ NPC exosome in a paracrine manner, thus impairing NPC tumor angiogenesis." (PMID 34975330, 2022). "Thus, we explored whether the LBH gene is correlated with EMT, angiogenesis and VEGFA expression in NPC tumor xenografts." (PMID 34975330, 2022).
cancer (12 papers, 2013 to 2024). A tumor composed of atypical neoplastic, often pleomorphic cells that invade other tissues. "We queried LBH gene mutations in 90,279 samples from 202 studies, covering the entire set of available cancers." (PMID 37268816, 2023). "We included in these analyses cell lines models for pancreatic (BxPC3, MIAPaCa2, PANC1), esophageal (TE7), and gastric (AGS, MKN45) cancer, as these cancer types also showed prognostically significant association between LBH expression and WNT gene signatures." (PMID 37268816, 2023). "To uncover the mechanisms underlying the dysregulated LBH expression in different cancer types, we analyzed genetic alterations in LBH using cBioPortal." (PMID 37268816, 2023). "Future studies are needed to address the mechanisms underlying the potential dual roles of LBH within certain cancer types." (PMID 37268816, 2023). "Next, we analyzed the frequency of LBH gene mutations, selecting the top 20 cancer types with at least 100 patient cases and covering a total of 15,597 samples." (PMID 37268816, 2023). "The LBH gene was altered in only 40 queried samples, with a somatic mutation frequency of 0.04%, indicating that LBH mutations in cancer are rare." (PMID 37268816, 2023). "Our pathway analysis in >10 different cancer types revealed a universal, positive association between LBH overexpression with both the WNT and Integrin/Focal Adhesion signaling pathways." (PMID 37268816, 2023). "We then overlapped these gene clusters from at least three different cancers using PANTHER to identify common LBH-associated pathways." (PMID 37268816, 2023). "LBH overexpression, observed in a broad spectrum of malignancies, including those affecting the GI tract, is associated with a poor prognosis and suggests its potential as a biomarker for Wnt hyperactivation in cancer patients." (PMID 39767561, 2024). "Notably, sites in LBH-associated CpG islands showed lower methylation in all four cancer types, in association with poor prognosis." (PMID 37268816, 2023). "LBH is a cancer‐associated factor and participates in the development of multiple cancer models." (PMID 34739189, 2022). "The involvement of LBH, a developmental transcription cofactor, further highlights the complexity of the Wnt pathway in cancer." (PMID 39767561, 2024). "Since The Cancer Genome Atlas (TCGA) is the landmark of cancer genomics with an extensive collection of open-source RNA sequencing data, we compared the LBH expression profiles from Oncomine with data in TCGA via GEPIA2." (PMID 37268816, 2023). "In cancers with LBH overexpression, the LBH locus was frequently hypomethylated, identifying DNA hypomethylation as a potential mechanism for LBH dysregulation." (PMID 37268816, 2023). "We found that DNA methylation levels at the LBH locus were significantly lower in LBH overexpressing cancers than in normal tissues." (PMID 37268816, 2023). "Collectively, these data indicate a widespread dysregulation of LBH expression in cancer, whereby it is overexpressed in most cancer types except for a few." (PMID 37268816, 2023). "Limb-Bud and Heart (LBH) is a highly conserved, tissue-specific transcription cofactor in vertebrates involved in development and misregulated in cancer." (PMID 37268816, 2023). "We extended our analysis to a total of 10 LBH overexpressing cancer types to examine the consistency and universality of LBH-associated signaling pathways." (PMID 37268816, 2023). "To further validate LBH-specific DNA hypomethylation in LBH overexpressing cancers, we performed methylation-specific qPCR (MSP) in normal and tumorigenic gastrointestinal cell lines." (PMID 37268816, 2023). "Independent KEGG analysis confirmed the WNT and Integrin (= Focal Adhesion) signaling pathways as top LBH-coexpressed pan-cancer gene signatures." (PMID 37268816, 2023). "We first queried individual cancer datasets from TCGA to identify LBH co-expressed genes using the R2 platform with Bonferroni correction and a p-value < 0.01." (PMID 37268816, 2023).
cancer (continued). "To assess the degree of LBH dysregulation in cancer, we examined its mRNA expression in all available cancer gene expression data using the visualization tools from the Oncomine gene expression database." (PMID 37268816, 2023). "To determine if increased LBH gene hypomethylation in LBH overexpressing cancers had prognostic value, we analyzed LBH-specific DNA methylation sites in the four gastrointestinal cancers above." (PMID 37268816, 2023). "Since aberrant LBH overexpression showed the highest pan-cancer correlation with the WNT and Integrin signaling pathways, we explored the clinical and prognostic significance of these associations in more detail." (PMID 37268816, 2023). "Differential LBH expression in cancer compared to normal tissue (fold change >1.5; p-value < 0.05) was detected in over 20 different cancer types." (PMID 37268816, 2023). "This analysis confirmed LBH overexpression in fourteen, and LBH underexpression in six common cancer types, with > 90% consensus between the two databases." (PMID 37268816, 2023). "To identify potential targetable signaling pathways correlating with LBH deregulation in cancer, we performed a systematic analysis of LBH co-expressed genes across different cancer types." (PMID 37268816, 2023). "Collectively, these data reveal a high degree of LBH dysregulation in cancer and establish LBH as pan-cancer biomarker for detecting WNT hyperactivation in clinical specimens." (PMID 37268816, 2023). "LBH serves as a targeted factor of Wnt signaling to increase Wnt‐related cancer progression and repress mammary epithelial differentiation." (PMID 34739189, 2022). "KEGG analysis showed that LBH co-expressed genes were enriched in terms of local adhesion, proteoglycans in cancer, and participates in classical cancer pathways such as PI3K-Akt, Ras, and Rap1." (PMID 31119084, 2019). "In epithelial development and cancer, LBH is a direct target gene for the canonical Wingless/Int (Wnt) signaling pathway." (PMID 30984102, 2019). "Collectively, these results identify that DNA hypomethylation, particularly at LBH-specific CpG islands may contribute to aberrant LBH overexpression in cancer." (PMID 37268816, 2023). "Therefore, to validate the clinical association between LBH overexpression and WNT pathway activation in cancer, we performed IHC analysis in a cohort of CRC patients." (PMID 37268816, 2023). "Among the top twenty cancer types with differential LBH expression were also blood cancers." (PMID 37268816, 2023). "Thus, even in cancers with reported LBH underexpression there appear to be individual subtypes with LBH overexpression." (PMID 37268816, 2023). "Importantly, this study establishes LBH as a putative pan-cancer biomarker for detecting WNT signaling activity in clinical specimen." (PMID 37268816, 2023). "As WNT targeted drugs are in clinical trials, identification of LBH as a marker that could stratify patients for WNT-targeted anti-cancer therapy is of high clinical significance." (PMID 37268816, 2023). "These experimental data, together with our present, and previous meta-analyses, indicate that LBH may be a universal biomarker to detect WNT hyperactivation in cancer." (PMID 37268816, 2023). "LBH was overexpressed at both the mRNA and protein levels in cancer compared with normal tissues." (PMID 31119084, 2019). "Due to the heterogeneity of cancers, different pathways are involved in proliferation and metastasis in various types of cancer, which may be the reason for the diversity of LBH action." (PMID 31119084, 2019). "We speculate that many epigenome-directed genes behave like LBH to mediate the context-specific effects of TGF-β in cancer." (PMID 26686634, 2015).
cancer (continued). "Thus, epigenetic mechanisms facilitating DNA hypomethylation may play an important role in aberrant LBH activation in cancer." (PMID 37268816, 2023). "This is the first study in which LBH was shown to promote the upregulation of integrin α5β1 in GC cells, thereby activating the integrin/FAK/Akt signaling pathway, and in turn, promoting the proliferation and invasion of GC, indicating that LBH may be an important cancer-promoting factor in GC." (PMID 31119084, 2019). "However, the expression and function of LBH in most cancers remain unknown." (PMID 37268816, 2023). "Among them were five genes with known transcription factor activity (PBX3, HOXB3, LEF1, HOXA7, LBH) and three genes with oncogenic potential (PAPD7, PBX3, LEF1) for which a role in other cancers has been suggested previously." (PMID 32728112, 2020). "The expression of the Wnt/β-catenin pathway target genes, particularly those related to cancer, such as CD44, S100A4, MMP7, and LBH, was significantly increased in GC tumors compared with that in normal tissue." (PMID 30965636, 2019). "As reported by others, WNT5A, LBH, WISP1 and TCF4 were expressed at lower levels in ER+ cell lines compared to ER-ve cancer but also compared to immortalised normal breast cell lines, perhaps reflecting their ER-ve status." (PMID 23861811, 2013). "Notably, LBH upregulation in CRC, PAAD, ESCA, and STAD cancer lines coincided with both, increased β-catenin and TCF4 protein expression, as well as increased TOPFlash reporter activity, a measurement of β-catenin/TCF transcriptional activity." (PMID 37268816, 2023). "While low-tumorigenic RKO, and normal-derived pancreatic (HPNE), esophageal (EPC2), and gastric (GES-1) cell lines had no or very low levels of LBH protein, LBH was markedly increased in all cancer lines analyzed." (PMID 37268816, 2023). "Notably, LBH is a direct target gene of the oncogenic WNT/ß-catenin signaling pathway, and genetic studies, showing Lbh knockout attenuates WNT-induced mammary tumorigenesis, imply an important role for LBH in WNT-driven cancers." (PMID 37268816, 2023). "However, LBH expression in most cancer types remains unknown, impeding understanding of its mechanistic function Here, we performed systematic bioinformatic and TMA analysis for LBH in >20 different cancer types." (PMID 37268816, 2023). "Here we performed the first comparative analysis of LBH expression in >20 different cancer types, using meta-analysis of published gene expression data, TMA analysis, and experimental validation in cancer cell lines, revealing overexpression of LBH in most cancer types except for a few." (PMID 37268816, 2023). "Since cancer studies almost exclusively characterize EMT as dedifferentiation 34, the differentiation promoted by the LBH gene could be considered to indicate EMT inhibition in LBH-overexpressing NPC xenografts." (PMID 34975330, 2022). "Thus, genetic alterations may not be the driving force of LBH dysregulation in cancer." (PMID 37268816, 2023).
gastrointestinal tumor (2 papers, 2023). "Significantly, knockdown of β-catenin profoundly reduced the elevated LBH expression in gastrointestinal tumor lines, uncovering that LBH overexpression in gastrointestinal cancers is WNT-dependent." (PMID 37268816, 2023).
infection (2 papers, 2021 to 2022). The state of being infected such as from the introduction of a foreign agent such as serum, vaccine, antigenic substance or organism. "Ectopic LBH, αB-crystallin (CRYAB) and VEGFA expression was induced by lentiviral infection or plasmid transfection to explore their functions in modulating EMT and angiogenesis in NPC." (PMID 34975330, 2022).
blood cancers (1 paper, 2023). "Hence, in blood cancers LBH is both over- and under-expressed, depending on the subtype." (PMID 37268816, 2023). "Analysis of LBH expression in hematopoietic malignancies, for which data had been lacking, revealed that in blood cancers LBH is both over- and under-expressed in a subtype-specific manner." (PMID 37268816, 2023).
LBH also shares sentences with these, for which no sentence is quoted: systemic lupus erythematosus (2 papers); acute lymphoblastic leukemia (1); adult T-cell leukemia/lymphoma (1); B-cell acute lymphoblastic leukemia (1); bladder cancer (1); brain cancer (1); celiac disease (1); cervical cancer (1); cervical squamous cell carcinoma (1); cholangiocarcinoma (1); chronic lymphocytic leukemia (1); chronic myeloid leukemia (1); colon cancer (1); congenital heart disease (1); esophageal cancer (1); head and neck squamous cell carcinoma (1); hypopharyngeal cancer (1); infarction (1); lung squamous cell carcinoma (1); lymphoma (1); muscular dystrophy (1); myeloma (1); neurodegenerative disease (1); ovarian serous cystadenocarcinoma (1); paraganglioma (1); pheochromocytoma (1); rectal cancer (1); sarcoma (1); skin cutaneous melanoma (1); stomach cancer (1).
A further 3 diseases each share a sentence with LBH in 1 paper.